FGFR1 (fibroblast growth factor receptor 1)
Diseases named in the same sentence as FGFR1 in open-access papers (continued):
Sharing a sentence is not in itself a finding about the gene and the disease.
cancer (continued). "Our data confirm the applicability of T-Fc in the form of ADC as a highly effective drug delivery vehicle for targeting FGFR1-producing cancer cells." (PMID 33962559, 2021). "We demonstratethe applicability of our oligomeric drug carriers for efficient andselective deterioration of FGFR1-overproducing cancer cells by constructinga highly potent trimeric cytotoxic conjugate fused with monomethylauristatin E." (PMID 34855396, 2021). "Various studies measure the expression level of the FGF1 and FGFR1 in different cancers, including breast carcinoma, hepatocellular carcinoma and esophagus cancer." (PMID 34552869, 2021). "A phenotypical characterisation of the migrated subpopulations revealed that the majority of them were nestin and fibroblast growth factor receptor 1 positive, an indication of their cancer stem cell origin." (PMID 33637089, 2021). "Amplification and activation of fibroblast growth factor receptor 1 (FGFR1) have been reported in many cancers." (PMID 34729943, 2021). "FGFR1 abnormalities have been found in a variety of cancers and play an important role in the growth, angiogenesis, migration, and resistance to cancer therapies." (PMID 34114373, 2021). "Overexpression of FGFR1 is observed in numerous tumors and therefore this receptor constitutes an attractive molecular target for selective cancer treatment with cytotoxic conjugates." (PMID 34635096, 2021). "70% of patients had coamplifications of receptor tyrosine kinase or other cancer-promoting genes, including MET, KRAS, FGFR1, IGFR1, SRC and VEGFA18–20, potentially associated with resistance to EGFR-inhibitors." (PMID 33199443, 2021). "Phase I/II clinical trials have indicated that AZD4547 can target cancers, such as gastric/esophagogastric, bladder, gastric adenocarcinoma, lung and breast, with FGFR1 and -2 amplifications." (PMID 34830836, 2021). "We developed conjugates based on fibroblast growth factor(FGF2) with improved biophysical and biological properties for theefficient killing of cancer cells overproducing fibroblast growthfactor receptor 1 (FGFR1)." (PMID 34542998, 2021). "This suggests the potential of FGFR inhibitors, in particular in cancers with high-level FGFR1 amplification that would be more readily detectable in ctDNA, to enhance treatment efficacy." (PMID 32940689, 2021). "FGFR1, an oncogenic receptor tyrosine kinase, plays a fundamental role in the physiological processes and cancer progression." (PMID 34873170, 2021). "A significant association between disease prognosis and FGFR1 expression was noted in various cancer patients and the studies suggested that FGFR1 was an independent prognostic factor." (PMID 33989301, 2021). "Reported data indicate that cancer cells harboring FGFR1 amplifications can acquire resistance to FGFR inhibitors mediated by overexpression of NRAS, MET amplification, mutational inactivation of PETN, and activation of AKT." (PMID 34114373, 2021). "FGFR1 has been found to maintain the stem cell characteristics of cancer cells, through activation of MEK (mitogen-activated protein kinase kinase)/ERK pathways and forkhead box protein M1 (FOXM1) pathway." (PMID 33637089, 2021). "FGFR1 executes cancer-promoting actions in PDAC oncogenesis, and affects a number of biological behaviors." (PMID 33581689, 2021). "Inhibition of FGFR1 in combination with trametinib treatment induced cell death in KRAS-mutant cancer cells." (PMID 34830951, 2021). "These dataindicate that 3xGFPp_FGF1E_LPET_MMAE is a trackable,FGFR1-selective, highly potent, and fluorogenic cytotoxic conjugateagainst FGFR1-overproducing cancer cells." (PMID 34855396, 2021).
cancer (continued). "Our results show that T-Fc-vcMMAE fulfills the key criteria for the successful cytotoxic drug carrier in a targeted approach against FGFR1-positive cancer cells." (PMID 33962559, 2021). "Here, we have tested the potential of the T-Fc as a drug delivery platform for the treatment of FGFR1-positive cancers." (PMID 33962559, 2021). "This successful strategy was applied to construct tetrameric cytotoxic conjugate targeting FGFR1-producing cancer cells." (PMID 34635096, 2021). "Although PD173074 is always used as FGFR1 inhibitor, it can also block cancer cell proliferation via the FGFR4 signaling pathway." (PMID 32555680, 2020). "Our data provide novel insights into the mechanisms of intracellular trafficking of FGFR1 and constitute guidelines for development of highly internalizing antibody‐based drug carriers for targeted therapy of FGFR1‐overproducing cancers." (PMID 32511887, 2020). "A few ATP-independent FGFR1 inhibitors have been synthesized, which exhibited anti-cancer activity in vitro or in vivo." (PMID 33041789, 2020). "It is known that UCA1 can participate in cancer biology by interacting with multiple signaling pathways, such as the FGFR1/ERK signaling pathway and the TGF-β pathway." (PMID 32013985, 2020). "Secondly, we showed that the observed aberrant FGFR1 and PARP1 expression was associated with cancer stem cell-like phenotype, regulated DNA repair, and modulated the response to therapy in PDAC cells." (PMID 32276472, 2020). "In a phase II trial of AZD4547 in patients with advanced cancers with FGFR1–3 aberrations, PRs were observed in 4 of 48 (8%) patients, including 2 patients with FGFR mutations and 2 with FGFR3–TACC3 fusions." (PMID 32962091, 2020). "It is a member of the tyrosine kinase family and shares similar structural morphology with VEGFRs and platelet-derived growth factor receptors (PDGFRs), which implies the potential role of FGFR1 in the carcinogenesis of many human cancers." (PMID 32171280, 2020). "It has been widely proved that FGFR1 dysregulation is closely correlated with the development of various cancers by promoting cell proliferation, migration, differentiation, and survival." (PMID 33041789, 2020). "FGF2, which was highly expressed in both cancer 4 cells and CSCs, interacted with the receptor FGFR1 in osteoclasts." (PMID 33162821, 2020). "Overexpression of FGFR1 is one of the most frequent genetic aberrancies within the FGFR family in cancers." (PMID 33076489, 2020). "As a regulator for cell differentiation, proliferation, and adhesion, the Fgfr1 gene is one of the major regulatory genes for EMT in multiple cancer subtypes." (PMID 33584803, 2020). "Genetic aberrations of FGFR1 are more frequently observed in human cancers (2.86%), followed by alterations in FGFR3 (2.21%), FGFR2 (1.77%), and FGFR4 (1.54%)." (PMID 32962091, 2020). "Further conditioned medium (CM) from MC38 cancer cells was sufficient to induce Fgfr1 and Fgfr2 although with a longer time course." (PMID 32792542, 2020). "Overexpression of FGFR1 is observed in numerous tumors and thus constitutes an attractive molecular target for selective cancer treatment." (PMID 32511887, 2020). "Positive ratios of FGFR1-4 were also presented separately, and the expression pattern of FGFR1-4 varied a lot among the cancer types." (PMID 32596330, 2020). "We demonstrated that aberrant FGFR1 and PARP1 expression was associated with cancer stem cell-like phenotype, regulated DNA repair, and modulated response to therapy in PDAC cells." (PMID 32276472, 2020). "The FGFR1-amplified NCI-H1581 cancer cell line was first used to create a subcutaneous xenograft model in nude mice." (PMID 31438996, 2019). "The pathway Signaling by FGFR1 was enriched with cancer drivers and had a CT drug target with an interaction < 100 nM, BRAF (B-Raf Proto-Oncogene, Serine/Threonine Kinase)." (PMID 31214023, 2019).
cancer (continued). "Our findings in this study have demonstrated that miR-214-3p acts as a vital biological targeting inhibitor for FGFR1, which need further study for cancer treatment." (PMID 31492847, 2019). "High FGFR1 expression levels have been documented in many cancers including bladder and lung cancer due to gene amplification or deregulation at the transcriptional level." (PMID 30931252, 2019). "Using FGFR-dependent cancer cell lines, we found that 3D185 potently inhibited FGFR1/2/3 signaling and, accordingly, significantly inhibited FGFR-mediated cancer cell proliferation and HUVEC survival." (PMID 31438996, 2019). "This FGFR1 splicing event attracted attention during the past a couple of decades for their differential roles in cancer biology." (PMID 30713601, 2019). "Malignant tumors had significantly high FGFR1 expression compared to benign tumors by digital analysis (p < 0.001)." (PMID 30931252, 2019). "Considering that α6-integrin and FGFR1 are both involved in cancer stem cell biology of GBM, we analyzed the possibility that they coordinately regulate GBMSC." (PMID 30909436, 2019). "ERBB2 and FGFR1 are well-known receptor tyrosine kinases involved in the carcinogenesis of different types of cancers." (PMID 30850667, 2019). "The FGFR1 silencing mediated by siRNAs, as demonstrated in our study, is also one of the approaches to deactivate FGFR1 in cancer." (PMID 31138759, 2019). "In BC, amplification of receptor tyrosine kinases, such as ERBB2, EGFR, IGFR and FGFR1, and/or their upregulation contribute to cancer initiation and progression." (PMID 35582269, 2019). "Alterations in FGFR1–4 are frequently detected in variety of developmental diseases and cancers, like prostate, breast, lung, and ovarian cancers." (PMID 31091809, 2019). "Whole-genome analyses of patient samples have revealed that the number of FGFR mutations and amplifications are generally very low in GBM (FGFR1: 51/3068 samples, FGFR2: 12/2662; FGFR3: 16/2887; FGFR4: 9/2456; cancer.sanger.ac.uk;)." (PMID 31337028, 2019). "Our goal was to design a batch of novel tyrosine kinase inhibitors that simulate adenosine triphosphate (ATP) and suppress the constitutive activation of FGFR1, thereby blocking the FGFR1-driven cancer signalling pathway." (PMID 29734851, 2018). "The main aim of this study was to assess the cytotoxic potency of α-amanitin/MMAE-FGF2 conjugate against cancer cell lines showing overexpression of FGFR1." (PMID 30029518, 2018). "The dual warhead conjugate binds to FGF receptor 1 (FGFR1) and utilizes receptor-mediated endocytosis for selective internalization into cancer cells with FGFR1." (PMID 30029518, 2018). "At day 7 and 14, E171 up-regulates genes in cancer signalling pathways such as chemical carcinogenesis and FGFR1/1c/3 and 3c ligand binding." (PMID 29950665, 2018). "We have recently proposed FGF2, natural ligand of FGFRs as an alternative targeting factor for selective delivery of cytotoxic agents into FGFR1-overproducing cancer cells." (PMID 30029518, 2018). "The single drug-FGF2 conjugates have no impact on the viability of NCI-H446 cells, whereas the dual warhead-FGF2 conjugate selectively and efficiently kills these FGFR1 positive cancer cells." (PMID 30029518, 2018). "We have demonstrated that these antibodies are effectively taken up by cancer cells in the FGFR1-dependent manner." (PMID 29748524, 2018). "Fibroblast growth factor receptor 1 (FGFR1) has become a potential target for the treatment of cancer." (PMID 29584670, 2018). "This study complements other FGFR1 studies that demonstrate genomic profiling as an approach to further understand, classify, and treat cancer of the head and neck." (PMID 29351293, 2018). "Designing FGFR1-selective inhibitors remains fundamental to the development of anti-cancer drugs because of highly sequential homology among FGFR subtypes." (PMID 29584670, 2018).
cancer (continued). "As a potentially relevant example, published studies reveal exquisite in vitro sensitivity of FGFR1-dependent cancer cell lines to FGFR-specific TKIs, although their in vivo sensitivity to these drugs was rather modest." (PMID 29458371, 2018). "For example, in cancers with FGFR1 amplification, only one patient responded to AZD4547, an FGFR1–3 inhibitor, among 20 patients with FGFR1-amplified squamous NSCLC." (PMID 30404198, 2018). "FGFR1 signaling plays a crucial role in maintaining cancer properties, such as cell survival, angiogenesis, and metastasis, in a variety of cancers." (PMID 30484492, 2018). "Nuclear FGFR1 regulates the transcription of a precise set of target genes critical for aggressive behavior of cancer cells." (PMID 30577533, 2018). "Our results on FGFR1-positive cancer cell lines show that the conjugate is efficiently targeting cells expressing FGFR1, leading to excellent and selective toxicity due to the combined cytotoxic effect of MMAE and α-amanitin." (PMID 30029518, 2018). "The proportion of African American in this study is higher than in previously published studies of FGFR1 copy number in various types of cancer." (PMID 29351293, 2018). "Anti-FGFR1 aptamers were also developed for the specific recognition of FGFR1-overproducing cancers." (PMID 30577533, 2018). "Extensive studies on FGFR1 have well documented its oncogenic features in different types of human cancer, including blocking apoptosis and promoting stemness, proliferation, drug resistance, migration/invasion, EMT, and angiogenesis." (PMID 30574019, 2018). "FGFR1, a tumorigenic receptor tyrosine kinase, plays an important role in some physiological processes and progression of cancer." (PMID 30210273, 2018). "For example, the lncRNA with the highest alteration frequency in LUSC, SOX2‐OT, was amplified in 45.6% of samples, which is higher than the cancer gene FGFR1 with frequency of 17.8%." (PMID 30216655, 2018). "As regorafenib potentially inhibits tumor growth through anti‐angiogenesis, several angiokinases such as VEGFR1/2, PDGFR‐β, and FGFR1 are believed to be major targets of regorafenib in cancer treatment." (PMID 29573334, 2018). "Genetic variations, including gene amplification and chromosomal translocation, increase FGFR1 expression and make it an ideal therapeutic target in several human cancers." (PMID 30574019, 2018). "Fibroblast growth factor receptor 1 (FGFR1) amplification is one of the most common genetic alterations in human cancers." (PMID 29351293, 2018). "The percentages of RAS mutated cases were 50% and 29% among primary cancer with FGFR2 and FGFR1 overexpression, respectively." (PMID 30181810, 2018). "Currently, the data available on the involvement of FGFR1 signaling in cancer glucose metabolism concern the enzyme PKM2, which catalyzes the final step of the glycolytic pathway, the conversion of phosphoenolpyruvate and ADP to pyruvate and ATP." (PMID 29190880, 2017). "The investigators made several conclusions, first that the compensatory response involving FGFR1 appears specific to particular KRAS-mutant cancer histologies." (PMID 28030802, 2017). "The efficacy of ponatinib against multiple tyrosine kinases, such as ABL, PDGFRα, VEGFR2 and FGFR1 has been illustrated in several adult cancer types." (PMID 27564113, 2017). "Collectively our results indicate that inhibition of FGFR1 signaling impacts on cancer cell growth also by affecting glucose energy metabolism." (PMID 29190880, 2017). "FGFR1 inhibitors are currently under development and studied in multiple cancers as treatment options." (PMID 29085059, 2017). "Combining autophagy inhibitors with FGFR1 selective inhibitors identifies a potential strategy for treatment of FGFR1-amplified cancers." (PMID 28558758, 2017). "The fibroblast growth factor receptor 1 (FGFR1) is frequently overexpressed in various types of human cancers." (PMID 27376150, 2016).
cancer (continued). "Multivariate Cox regression analysis demonstrated FGFR1 positive luminal A cancers to be an independently poor prognosticator for disease free survival in luminal cancers (hazard ratio = 3.341, p = 0.008)." (PMID 26673008, 2016). "Since it is less likely for cancer cells to develop acquired resistance when multiple RTKs are simultaneously inhibited up front, there is a rationale for using the PDGFRα and FGFR1 inhibitor combination as first-line therapy." (PMID 27783942, 2016). "MiR-216b-mediated repression of FGFR1 is therefore mitigated, leading to an increased level of FGFR1 in the cancer cells." (PMID 26978351, 2016). "Significant difference in FGFR1 expression was found among different molecular subtypes (p < 0.001), with the highest expression rate seen in Lum B cancers." (PMID 26673008, 2016). "In particular, an increasing number of novel FGFR1 fusion genes have been identified by RNA-Seq analysis in different types of cancers." (PMID 27391347, 2016). "The worse DFS in FGFR1 expressing Lum A cancers was comparable to that of luminal B cancers (compared to FGFR1-expressing luminal B: log-rank = 0.324, p = 0.569; FGFR1 negative luminal B: log-rank = 0.056, p = 0.812)." (PMID 26673008, 2016). "FGF2/FGFR1 nuclear translocation is vital to activation of PSCs, which is required for cancer progression." (PMID 27061193, 2016). "Apart from FGFR1, other genes overexpressed in Lum B have also shown to affect cancer growth and patients outcome." (PMID 26673008, 2016). "The Nanostring cancer progression gene panel revealed a dramatic upregulation of fibroblast growth factor receptor 1 (FGFR1) and its cognate ligand FGF2 in both acquired and inherent resistance." (PMID 27825137, 2016). "A significant association of FGFR1 with ER and Ki67 in the overall cohort while significant correlation with low PR and high Ki67 as well as a near significance with HER in luminal cancers were observed." (PMID 26673008, 2016). "FGFR1 staining is present on more differentiate areas of the cancer, but lost in more transformed, and invasive regions." (PMID 25973543, 2015). "The confirmation that FGFR1 is over-expressed in cancer cells prompted us to develop a neutralizing antibody for FGFR1 intervention." (PMID 26201468, 2015). "Proliferation assay and apoptosis analysis were performed to assess the effect of IMB-R1 on cancer cell growth and apoptosis, respectively, in comparison with known FGFR1 inhibitors." (PMID 26201468, 2015). "MG63 expressed the greatest levels of FGFR1 transcripts of all the cells tested, and was thus selected as the representative cancer cell model in subsequent assays." (PMID 26201468, 2015). "IMB-R1 differs from other existing FGFR1-neutralizing antibodies in that it expressly disrupts HS-FGFR1 interactions, highlighting the importance of targeting heparin-binding sites as a potential anti-cancer strategy." (PMID 26201468, 2015). "FGFR1 is one of the most widely expressed FGFRs, and here we confirmed that FGFR1 is strongly expressed in both normal and cancer tissues." (PMID 26201468, 2015). "An overall high FGFR1 expression level in amplified cancers was mainly driven by two FGFR1 amplified cancer with particularly high mRNA expression levels." (PMID 26555375, 2015). "Immunohistochemical staining of FGFR1 using IMB-R1 were carried out in different cancer tissues from clinical patients." (PMID 26201468, 2015). "We found FGFR1 amplification in six of eight samples of squamous cell dysplasia adjacent to FGFR1 amplified cancers, and 15 of 18 FGFR1 amplified ESCC showed homogeneous amplification." (PMID 26555375, 2015). "Our study suggests that blocking HS interaction with the heparin-binding domains of FGFR1 inhibited cancer cell growth, which can be an attractive strategy to inactivate cancer-related heparin-binding proteins." (PMID 26201468, 2015). "All 23 amplified cancers were further analyzed in order to assess the level of homogeneity/heterogeneity of FGFR1 amplifications." (PMID 26555375, 2015).